ALB (albumin)
Diseases named in the same sentence as ALB in open-access papers (continued):
Sharing a sentence is not in itself a finding about the gene and the disease.
Sepsis (continued). "Considering the individual importance of lactate and albumin in sepsis prognosis, their combined assessment through the lactate/albumin (L/A) ratio could potentially offer a composite marker that mirrors both the metabolic and physiological status of septic patients." (PMID 38518050, 2024). "Hepatic malignancy and cirrhosis which tend to influence the generation of albumin and bilirubin; sepsis, AMI, and other complications which may exert significant influence on mortality; SOFA, SAPSSII score, and a few blood biomarkers like lactate which will reflect the severity of illness." (PMID 39055134, 2024). "Serum albumin levels tend to be low on average in studies of patients with sepsis in ICUs, where a longer interval between the start of infection and serum albumin measurement, and especially the current use of large volemic treatments, tend to reduce albumin’s information capacity." (PMID 38137746, 2023). "Moreover, there is evidence supporting the albumin treatment in sepsis patients." (PMID 37089426, 2023). "Therefore, this study aims to evaluate prognostic risks in sepsis patients more comprehensively by analyzing the relationship between the ferritin-to-albumin ratio and the 28-day mortality rate, thereby mitigating the influence of individual factors on sepsis prognosis." (PMID 37817258, 2023). "Similarly, albumin synthesis may be impaired by concomitant liver disease, nutrition status, infection, and specifically in sepsis." (PMID 37108536, 2023). "Furthermore, albumin correlated with important ICU scores such as the sepsis-related organ failure assessment (SOFA) (r = −0.409; p 0.001), acute physiology (r = −0.339; p 0.001), and the acute physiology and chronic health evaluation II (APACHE II) scores (r = −0.413; p 0.001)." (PMID 37108536, 2023). "The SAFE study indicated that patients with sepsis may benefit from albumin replacement." (PMID 37218881, 2023). "More recently, the effects of VLC with elastic bandages compared to hypertonic albumin on diuretic efficiency were evaluated in a large retrospective cohort of patients (N = 1147) with volume overload and diuretic resistance during the de-escalation phase of sepsis resuscitation." (PMID 35872894, 2022). "Finally, albumin depletion in sepsis was strongly correlated with a decrease in plasma free thiols at the ED, suggesting that thiol depletion could at least be partially attributed to lower albumin levels." (PMID 35624664, 2022). "However, no recent study has addressed the association between ALB levels and death in sepsis patients with AKI undergoing CRRT alone." (PMID 35109818, 2022). "Additionally, we also evaluated the ability of CRP and ALB to predict severe sepsis." (PMID 35873709, 2022). "The effects and safety of albumin infusion in patients with sepsis and CHD remain unclear." (PMID 36337861, 2022). "Albumin levels in sepsis were correlated with plasma free thiol levels upon ED admission, which suggests that the observed thiol depletion may be at least partially attributed to lower levels of albumin." (PMID 35624664, 2022). "Thus, albumin depletion in sepsis was correlated with a decrease in plasma free thiol levels." (PMID 35624664, 2022). "Importantly, there is emerging evidence that a novel marker termed “LAR,” that is, the ratio of lactate to albumin, is established and preferably used in predicting mortality of critically ill patients, including cardiac arrest, shock, sepsis, and traumatic brain injury." (PMID 36324387, 2022). "Therefore, we decided to find out if contained in the plasma of sepsis and septic shock patients, albumin that normally shows an average molecular weight of 66.5 kDa, might contain bound-peptides derived from the C-terminal segment of CETPI." (PMID 36536294, 2022).
Sepsis (continued). "In veterinary medicine, studies have been conducted to investigate the usefulness of bilirubin, albumin, cholesterol, serum amyloid A, C-reactive protein, serum C-type natriuretic peptide, protein C and antithrombin concentrations as prognostic biomarkers for sepsis." (PMID 36423076, 2022). "However, albumin infusion in patients with sepsis and CHD has rarely been studied." (PMID 36337861, 2022). "A total of 1055 sepsis patients were enrolled and allocated into two groups based on the lowest in-hospital albumin level: 924 patients were in the hypoproteinemia group (the lowest in-hospital albumin ≤ 3.1 g/dL) and 131 patients were in the normal group (the lowest in-hospital albumin > 3.1 g/dL)." (PMID 34934165, 2021). "Albumin blood level may be one of the indicators for evaluating sepsis severity." (PMID 34934165, 2021). "The most recent Surviving Sepsis Campaign recommendations state that albumin in addition to crystalloids may be considered in limited quantities for early resuscitation and subsequent intravascular volume replacement in people with sepsis or septic shock." (PMID 33959654, 2021). "However, a systematic review suggested that the patients with severe sepsis might benefit from the fluid therapies with albumin." (PMID 34869452, 2021). "Therefore, CRP/ALB ratio has been recently identified as a valuable predictor of prognosis in patients with various diseases such as tumor and sepsis 10,17,18, whereas its prognostic role remains unclear in AECOPD patients with HF." (PMID 33746575, 2021). "When separating AKI patients into groups with and without sepsis, we observed that patients with sepsis-associated AKI had lower levels of albumin-adjusted free thiol levels (6.8 (2.0, 7.9) μmol/g) compared to patients without both sepsis and AKI (8.4 (5.8, 10.8) μmol/g; p < 0.05)." (PMID 33207555, 2020). "Moreover, as thiols are influenced by serum albumin levels, which might be affected by critical illness or sepsis, we corrected the thiol levels for albumin, in contrast to previous studies." (PMID 33207555, 2020). "However in cirrhotic patients with any infection, albumin use may significantly reduce sepsis related mortality and renal impairment." (PMID 32704299, 2020). "Among the studied diagnostic variables, UP/CR, albumin, TaMin, RLeng/AorRatio, pulsatility index, TaMax, haematocrit, hemoglobin, leukocytes, and CortPeak exhibited an accurate predictive value for AKI diagnosis (>80% accuracy) in patients with sepsis/pyometra." (PMID 32488080, 2020). "This may be a potential hypothesis for the prognostic role of albumin in sepsis." (PMID 32454793, 2020). "However, CRP, PCT, and ALB levels, 14-day mortality rates, and sepsis-associated coagulopathy would not be affected by the judgments of physicians." (PMID 32778146, 2020). "Multiple factors which may be associated with anastomotic leak include number of preoperative comorbidities, levels of hemoglobin and albumin, location of tumor, type of conduit, anastomotic technique (hand sewn versus stapled), institutional and surgeon volume, and sepsis." (PMID 32024132, 2020). "A rise to average albumin levels we predict could alleviate systemic sepsis and prevent death." (PMID 33088822, 2020). "The treatment of sepsis in Japan involves the use of blood component preparations (red blood cell concentrate, fresh-frozen plasma, and platelet concentrate) as well as plasma fraction preparations (albumin preparations, immunoglobulin preparations, and antithrombin preparations)." (PMID 29435330, 2018). "Moreover, the follow up may not have been long enough to address this due to the long half-life of serum albumin and the fact that changes in serum albumin under the study condition may occur very slowly (in contrast to sepsis and other acute conditions)." (PMID 30515432, 2018).
Sepsis (continued). "Hence, many studies have recently investigated whether the ratio of CRP to ALB can effectively reflect the prognosis of critically ill patients diagnosed with severe sepsis or septic shock." (PMID 29495423, 2018). "Given that clinical formulations of albumin are in saline, our objectives were to develop a novel balanced electrolyte solution specifically for sepsis and to determine if supplementing this solution with albumin would improve the inflammatory response in sepsis." (PMID 28105603, 2017). "At least two mechanisms may contribute to an increased extravasation of albumin in sepsis." (PMID 29075932, 2017). "For patient type 1 who needs volume expansion in the absence of blood loss and sepsis, most physicians (63–78 %) chose crystalloids as their first choice of intravenous (IV) fluids regardless of clinical specialty, followed by 5 % albumin (9–13 %)." (PMID 27313844, 2016). "Therefore, blood lactate might be also negatively correlated with albumin during the acute phase of sepsis." (PMID 26557421, 2015). "We investigated the use of the CRP/albumin ratio as an independent predictor of mortality in these patients where we hypothesized that this ratio could be used as an independent predictor of mortality in patients with severe sepsis or septic shock." (PMID 26158725, 2015). "However, post hoc analysis of the sepsis subgroup indicates that resuscitation with albumin may reduce the mortality in patients with severe sepsis, confirming possible additional protective mechanisms conferred by albumin." (PMID 25180196, 2014). "Most recently, a cost-effectiveness analysis in severe sepsis and septic shock using an advanced Bayesian approach observed life-years gained with albumin relative to crystalloid therapy, and concluded that albumin may be the most cost-effective intravenous solution in this patient population." (PMID 25042164, 2014). "Collectively, these findings indicate that septic pulmonary MVEC death, putatively apoptosis, is a result of leukocyte activation and iNOS-dependent signaling, and in turn, may contribute to pulmonary microvascular barrier dysfunction and albumin hyper-permeability during sepsis." (PMID 24516666, 2014). "However, until recently, the pragmatic value of albumin in sepsis is still under debate." (PMID 25474401, 2014). "Our results suggest that septic apoptosis of the pulmonary MVEC may be a result of leukocyte activation and iNOS-dependent signaling, and in turn, may contribute to pulmonary microvascular barrier dysfunction and albumin hyper-permeability in sepsis-induced lung injury." (PMID 24516666, 2014). "Therefore, CRP and serum albumin levels should diverge during sepsis." (PMID 23555017, 2013). "Capillary leakage may reduce plasma volume; however, colloids (albumin) have been shown in patients with sepsis to increase the interstitial and plasma volumes more than the volume of infused fluids, possibly because of movement of fluid from the intracellular compartment." (PMID 23327106, 2013). "Comparative diagnostic accuracy of urine albumin:creatinine ratio (ACR) variables for the differential diagnosis of sepsis after ICU admission: For all patients, the area under the ROC curve (AUC) to distinguish sepsis was highest for ACR1 (0.702) followed by ACR2 (AUC 0.612) and ΔACR (AUC 0.681)." (PMID 20606905, 2010). "More recent evidence suggests that human albumin increases mortality in patients with traumatic brain injury and that some hydroxyethyl starch solutions may increase the incidence of renal failure in patients with severe sepsis." (PMID 20950434, 2010). "In the present study, we found that, during experimental sepsis, the antibody-mediated blockade of anaphylatoxin C5a prevented breakdown of the blood-brain barrier, reducing cerebral and pituitary edema formation, as assessed by extravasation of albumin and EB." (PMID 19196477, 2009).
Sepsis (continued). "The levels of TAC, uric acid, albumin, and bilirubin in sera were obtained in the emergency department and evaluated to determine whether there were any correlations between the major antioxidant biomarkers and clinical severity of sepsis." (PMID 16507162, 2006). "Lactate dehydrogenase-to-albumin ratio (LAR), which combines 2 routine laboratory tests, has recently been suggested as a prognostic marker in sepsis." (PMID 41496084, 2026). "The albumin–bilirubin (ALBI) score, an evidence-based index of hepatic function and systemic inflammation, has shown prognostic value in sepsis." (PMID 41933308, 2026). "In recent years, the lactate-to-albumin ratio (LAR) has emerged as a novel prognostic marker in various critical illnesses, including sepsis, heart failure, and acute respiratory failure." (PMID 41813814, 2026). "However, the optimal range of serum albumin levels in sepsis patients remains unknown." (PMID 40978746, 2025). "In sepsis, CRP increases and positively correlates with the degree of infection, while ALB is often decreased." (PMID 40351994, 2025). "The AUC of LAR was more and found to be better in predicting need of mechanical ventilation in sepsis in comparison to lactate alone (AUC: 0.881 v/s 0.857), SOFA score (AUC: 0.881 v/s 0.689), albumin alone (AUC: 0.881 v/s 0.631)." (PMID 40130722, 2025). "The LAR was more and found to be better in predicting need of inotropes among patients diagnosed with both sepsis and ARF in comparison to lactate alone (AUC: 0.849 v/s 0.810), SOFA score (AUC: 0.849 v/s 0.609), albumin alone (AUC: 0.849 v/s 0.710)." (PMID 40130722, 2025). "This study investigated the association between the red blood cell distribution width-to-albumin ratio (RAR) and mortality in critically ill cirrhotic patients with sepsis." (PMID 40636366, 2025). "The LAR was more and found to be better in predicting need of mechanical ventilation among patients diagnosed with both sepsis and ARF in comparison toSOFA score (AUC: 0.874 v/s 0.649), albumin alone (AUC: 0.874 v/s 0.602)." (PMID 40130722, 2025). "The key predictive factors for sepsis included the SOFA score, new onset shock, albumin, blood urea nitrogen (BUN), third-degree burned area, TBSA burned, white blood cell count, and inhalation injury." (PMID 40901002, 2025). "The fibrinogen-albumin ratio (FAR) is recognized as a prognostic biomarker in several diseases, but its role in sepsis remains controversial." (PMID 40607037, 2025). "In a study of 12246 patients with Sepsis, ACAG has the highest predictive value for in-hospital mortality of intensive care patients with sepsis, which is better than albumin and AG." (PMID 41401154, 2025). "The most commonly used replacement fluid was 5% albumin (92.7%), while three patients received fresh frozen plasma (FFP), selected based on the presence of coagulopathy and sepsis, conditions that require plasma factor replacement." (PMID 41210231, 2025). "In the non-survivor group, diuretic use (p = 0.03), oliguria, RRT, vasopressor requirement, sepsis, and MV rates (p < 0.001),as well as BUN, phosphate, LDH, Crp, APTT, INR, and BAR rates, were higher (all p < 0.05) and albumin was lower (p = 0.01)." (PMID 40731862, 2025). "The LAR was more and found to bebetter in predicting mortality among patients diagnosed with both sepsis and ARF in comparison to lactate alone (AUC: 0.853v/s 0.790), SOFA score (AUC: 0.853 v/s 0.664), albumin alone (AUC: 0.853 v/s 0.734)." (PMID 40130722, 2025). "To date, there are no published randomized controlled trials that have established a link between albumin use and SA-AKI development in sepsis." (PMID 40841985, 2025). "The sepsis group had decreased ALB and MBP values and higher HCT-ALB values and SOFA scores than in the non-sepsis group." (PMID 41294166, 2025).
Sepsis (continued). "Given the lack of benefit and potential hazards associated with early albumin use in ischemic stroke patients, we hypothesize that the addition of albumin, whether early or not, will not enhance survival in ischemic stroke patients with sepsis." (PMID 41468394, 2025). "ROC curves were performed to evaluate the predictive value of albumin, AG, and ACAG for in-hospital mortality in patients with Sepsis-AKI." (PMID 40680007, 2025). "ROC curve analysis was conducted to evaluate the predictive value of LDH, ALB, and LAR for neonatal sepsis mortality." (PMID 40307261, 2025). "Several biomarkers have been explored for their prognostic value in sepsis, including C-reactive protein (CRP), albumin, and lymphocyte count." (PMID 40310418, 2025). "Albumin was the most commonly used replacement fluid (92.7%); however, fresh frozen plasma (FFP) was used in three patients due to the presence of sepsis and coagulation abnormalities, conditions that require plasma factor replacement." (PMID 41210231, 2025). "ACAG demonstrates the greatest predictive accuracy for in-hospital mortality among patients with Sepsis-AKI, outperforming both albumin and AG." (PMID 40680007, 2025). "Thus, it can be seen that ALB may be a useful biomarker in predicting the severity of sepsis." (PMID 40438354, 2025). "In an endotoxin model of sepsis, PEG-conjugated albumin also exhibited better microvascular effects than dextran." (PMID 41247634, 2025). "The AUC of LAR was more and found to be better in predicting requirement of inotropes in sepsis in comparison to lactate alone (AUC: 0.819 v/s 0.789), SOFA score (AUC: 0.819 v/s 0.672), albumin alone (AUC: 0.819 v/s 0.614)." (PMID 40130722, 2025). "The AUC of LAR was more and found to be better in predicting mortality in sepsis in comparison to lactate alone (AUC: 0.914 v/s 0.873), SOFA score (AUC: 0.914 v/s 0.730), albumin alone (AUC: 0.914 v/s 0.715)." (PMID 40130722, 2025). "We carefully excluded patients who developed AKI prior to the diagnosis of sepsis to reduce potential confounding effects on the serum levels of LDH and albumin." (PMID 38898431, 2024). "In recent years, there has been considerable interest in utilising the C-reactive protein (CRP)/albumin ratio (CAR) to evaluate the condition and forecast the prognosis of patients with sepsis." (PMID 38938850, 2024). "Deceased patients with sepsis secondary to BSI have significantly elevated levels of CRP, lower serum albumin concentrations, and significantly higher mean CRP/albumin ratio." (PMID 39252713, 2024). "The fibrinogen-to-albumin ratio (FAR) has been identified in several studies as a predictor of poor outcomes and adverse events in patients with cardiovascular diseases, sepsis, stroke, and cancer." (PMID 38611583, 2024). "Other studies have similarly indicatedthat the lactate/albumin ratio could be used to predictpoor prognosis in pediatric septic shock patients, implying that the lactate/albumin ratiocould also be used as a predictor of poor prognosis inpediatric or adult sepsis patients." (PMID 39139159, 2024). "According to the current study, RAR has greater predictive value for in-hospital, 28-day, and 90-day mortalities in patients with sepsis, as its area under the ROC curve exceeded that of RDW or albumin alone." (PMID 38877408, 2024). "Age, dyspnea at rest, preoperative sepsis, III/IV/V of American Society of Anesthesiologists physical status, and albumin and creatinine were selected for the final model." (PMID 39116449, 2024). "Multivariate Cox proportional hazards analysis showed that age, albumin levels, APACHE II score, and SIC on day 4 were independent predictors of 28-day mortality in patients with sepsis." (PMID 38438863, 2024). "When combined with albumin, the predictive specificity reached an impressive 87.50% and improved the predictive value of ICU mortality in sepsis-induced ARDS patients." (PMID 39686985, 2024).